CNTNAP2 (contactin associated protein 2)
Diseases named in the same sentence as CNTNAP2 in open-access papers (continued):
Sharing a sentence is not in itself a finding about the gene and the disease.
autism (continued). "Reduction in social/non-social neuronal proportion in mPFC is a phenomenon that is shared by several autism mouse models, such as Shank2-KO and Cntnap2-KO mice, and therefore, may be causally related to the social impairment seen in IRSp53-KO mice." (PMID 36317872, 2022). "CNTNAP2, a gene that encodes a member of the neurexin family with functions linked to the nervous system, has been implicated in several neurodevelopmental disorders including schizophrenia, autism, ADHD and depression." (PMID 34696705, 2022). "Among other possibilities, antibodies to neuronal surface protein Contactin Associated Protein 2 (CASPR2) have been found more frequently in mothers of children with neurodevelopmental disorders or autism, and two independent experimental studies have shown pathogenicity in mice." (PMID 32784803, 2020). "CNTNAP2 is required for radial and longitudinal organization of myelinated axons and has been associated with AD and other disorders such as epilepsy, seizures, autism and schizophrenia, and common variants in this gene influence early language acquisition." (PMID 33218114, 2020). "Our analysis supports the role of several genes/loci associated with autism (e.g., NRXN1, ADNP, 22q11 deletion) and identified new truncating (e.g., GRIK2, ROBO1, NINL, and IMMP2L) or recessive deleterious variants (e.g., KIRREL3 and CNTNAP2) affecting autism-associated genes." (PMID 30675382, 2019). "Interestingly, research has also implicated CNTNAP2 in multiple neurodevelopmental disorders, including Gilles de la Tourette syndrome, schizophrenia, epilepsy, autism, attention deficit and hyperactivity disorder, and mental retardation." (PMID 29695247, 2018). "Heterozygous mutations in CNTNAP2 are frequently associated with susceptibility to autism." (PMID 28358038, 2017). "We hypothesized that CNTNAP2, a protein associated with autism, would play a key role in this process." (PMID 25951243, 2015). "Consequently, this study suggests that although CNTNAP2 dysregulation plays a role in some cases, its population contribution to autism susceptibility is limited." (PMID 24147096, 2013). "Consequently, CNTNAP2 is a very large mutational target, and its restricted and early expression in the nervous system, potentially deregulated by mutations in autism, fit well with current understanding of autism pathobiology." (PMID 24147096, 2013). "Mutations in CNTNAP2 have been implicated in epilepsy, language regression and mental retardation, and Tourette's syndrome, and variants in the gene have been shown to be associated with age at first word in probands with autism." (PMID 24765219, 2013). "Interestingly, another member of the contactin family, CNTNAP2, has been found to be associated with both schizophrenia and autism." (PMID 23922650, 2013). "CNTNAP2 has been implicated in intellectual disability, cortical dysplasia-focal epilepsy syndrome and the related Pitt-Hopkins-like intellectual disability, autism and language impairment." (PMID 24083349, 2013). "The first report of CNTNAP2 as an autism susceptibility gene was in a study of children with autism in which the parents reported the age at which their child spoke their first word, which served as the phenotype for the association analysis of single nucleotide polymorphisms (SNPs)." (PMID 23176600, 2012). "Several lines of evidence have identified CNTNAP2 as an autism-susceptibility gene." (PMID 23074684, 2012). "Finally, elevated intensity was observed in at-risk carriers of an autism-associated CNTNAP2 allele in pACC." (PMID 22848344, 2012). "CNTNAP2 is associated with specific language impairment as well as with autism." (PMID 22937139, 2012). "In addition, rare recessive mutations in the CNTNAP2 gene appear to segregate with seizures, language regression, and autism in some Amish pedigrees, and to be associated with Pitt-Hopkins-like mental retardation." (PMID 23074684, 2012).
autism (continued). "Using a series of simulations, Bishop argued that CNTNAP2 may confer risk for SLI, but may also lead to autism only when there is a specific conjunction of a risk haplotype on CNTNAP2 with an autism risk haplotype on another gene." (PMID 21418292, 2011). "In addition, rare structural variants involving CNTNAP2 have also recently been associated with autism susceptibility, further implicating this gene family." (PMID 20346443, 2010). "The CNTNAP2 (contactin associated protein 2) gene (7q35) is a member of the neurexin family, which plays a crucial role in nervous system development as a cell adhesion and receptor molecule, and has been implicated in intellectual disability, epilepsy, schizophrenia, autism, and ADHD." (PMID 40631452, 2025). "In another study, homozygous CNTNAP2–/– mice exhibited reduced long-range and local functional connectivity in the prefrontal and midline brain regions, suggesting that homozygous loss-of-function mutations in CNTNAP2 predispose individuals to NDDs, such as autism." (PMID 37069342, 2023). "Furthermore, CNTNAP2 gene mutations are associated with autism." (PMID 24466509, 2014). "A thoroughly studied example of a gene repressed by FOXP2, CNTNAP2, has been implicated in disorders such as specific language impairment and autism, among others, which sheds some light on the mechanism through which FOXP2 may be influencing speech and language." (PMID 24765219, 2013). "Consequently, we designed a study to comprehensively search for genetic associations within the entire CNTNAP2 locus that could contribute to autism and ASD susceptibility." (PMID 24147096, 2013). "Critical confounders were unavailable in FAERS, such as family history of autism, concomitant medication use, autism-associated genetic variants (e.g., SHANK, NRXN, CNTNAP2, NLGN), as well as dose, duration of exposure, and relevant environmental factors." (PMID 41598838, 2026). "Contactin-associated protein-like 2 (CNTNAP2) is one of the first and most widely replicated genes associated with autism susceptibility." (PMID 41150744, 2025). "One genetic risk factor of ASD are variants in the contactin-associated protein-like 2 (CNTNAP2) gene, and a complete CNTNAP2 loss-of-function causes a syndromic disorder with core symptoms of autism." (PMID 40134417, 2025). "Pharmacological inhibition of this pathway reversed core autism-related phenotypes in Cntnap2−/− mice." (PMID 39758604, 2025). "With training, both Shank3B+/− and Cntnap2−/−mouse models of autism can learn to recognize weak target odors in the presence of strong background odors, transitioning from naive to experts and performing comparably to WT mice." (PMID 41062277, 2025). "Given evidence of slower processing speed in autism, this possible link to Cntnap2 should be considered in future studies." (PMID 40824873, 2025). "Abnormalities in development of auditory perception and reactivity in Cntnap2 knockout rats align with symptoms reported in humans with autism and suggests this gene should be one of interest in sensory processing studies." (PMID 39677787, 2024). "Remarkably, viral-driven expression of NECDIN in the Cntnap2−/− mouse model of autism normalized the social deficits of these mice." (PMID 38978588, 2024). "Current evidence suggests that the real-time modulation of the excitation-inhibition balance in the prefrontal cortex of Cntnap2-null mutant mice effectively alleviates social behavior deficits reminiscent of autism phenotypes." (PMID 39695746, 2024). "Our study revealed a critical role for CICD generated by γ-secretase cleavage of CNTNAP2 in the autism-related behaviors, as overexpression of CICD in the mPFC of Cntnap2−/− mice fully rescues the social deficit as well as repetitive behaviors." (PMID 37271769, 2023). "In the third part, we analyze the behavior of the Cntnap2−/− mouse model of autism in odor recognition in the presence of novel backgrounds." (PMID 36781878, 2023).
autism (continued). "Both these genes are associated with neurological diseases; (ERC1 with pontocerebellar hypoplasia type 2E and CNTNAP2 with Pitt–Hopkins-Like syndrome 1 and autism 1528)." (PMID 36774368, 2023). "Mice models of autism, such as SHANK or CNTNAP2, are strongly associated with intellectual disability." (PMID 37189195, 2023). "Our present findings demonstrate that both altered corticothalamic connectivity and expression of PNNs and GABAergic PV-positive interneurons in the primary sensory cortical regions are present in the CNTNAP2 KO mouse model of autism." (PMID 37371370, 2023). "The Prader Willi gene Necdin is one of such target genes and partly responsible for the deficit of autism-related behaviors in Cntnap2−/− mice, as overexpression of Necdin in the mPFC of Cntnap2−/− mice normalized the social deficit." (PMID 37271769, 2023). "We also used our task to investigate the performance of female Cntnap2-/- mice, which show some autism-like behaviors." (PMID 36781878, 2023). "The Cntnap2 KO rat model has a high face and constructs validity for core autism-related alterations in social and stereotypic behaviors, as well as in sensory filtering and sensorimotor gating." (PMID 37852987, 2023). "Intriguingly, lessons from Cntnap2 knockout mice show segregated contributions of host genetics and the microbiome to autism-related social behaviour." (PMID 36395738, 2022). "Both rare and common genetic variants in CNTNAP2 have been associated with neurodevelopmental disorders, with a special relevance in ADHD and autism." (PMID 36153331, 2022). "It has been also shown that exogenous and evoked OT restore social behavior in the Cntnap2 mouse model of autism." (PMID 35203614, 2022). "We studied sensory processing in the cerebellum in a mouse model of autism, knock-out (KO) for the Cntnap2 gene." (PMID 34593517, 2021). "In this work, we studied cerebellar integration of sensory information in the Cntnap2 mouse model of autism." (PMID 34593517, 2021). "For example, prolonged monitoring approaches help to uncover the interplay of genetic factors and time, like in a study of locomotor activity in four genetic mouse models for autism: Shank3−/−, Cntnap2−/−, Frm1−/−, and Pcdh10+/−." (PMID 34630052, 2021). "During each exposure, Cntnap2 KO mice were more active compared to WT in the 3 different contexts, further confirming an autism-like phenotype and persistence of these behavioral features after electrode implantation." (PMID 34758298, 2021). "For example, the contactin-associated protein-2 (CNTNAP2) gene, first associated with autism in the OOA/M37, has since been replicated in multiple studies in the general population." (PMID 31527585, 2019). "Heterozygous deletions encompassing the CNTNAP2 gene were described not only in autism but a wide range of phenotypes, including psychiatric or neurologic disorders, and language-related deficiencies." (PMID 30586385, 2018). "Given that CNTNAP2 remains a top candidate gene with regards to the molecular basis of autism, these homozygous patients would be of great value for studying the links between CNTNAP2 and autism." (PMID 26843181, 2016). "Here, we examined adult neurogenesis in the hippocampus, as well as astroglia and microglia in the hippocampus, mPFC, and striatum of two models that display autism-like phenotypes, Cntnap2−/− and Shank3+/ΔC transgenic mice." (PMID 27785461, 2016). "As exemplified by CNTNAP2 and NRXN1 gene, heterozygous missense variants confer susceptibility to autism while compound heterozygous mutations of CNTNAP2 and NRXN1 cause Pitts-Hopkins like syndrome." (PMID 27271878, 2016). "Rare mutations in other autism related genes such as CNTNAP2 and CHD8 are also associated with both autism and macrocephaly,while mutations in the risk genes AUTS2 and DHCR7 give rise to autism and microcephaly." (PMID 26076356, 2015).
autism (continued). "Mutants for neurexin IV (using Nrx-IV4304), the orthologue of the autism gene CNTNAP2, and w1118 were used as positive and wild type controls, respectively." (PMID 25816101, 2015). "We present here an assessment of the 16p11.2 df/+ and Cntnap2 -/- murine models of autism and compare results against those obtained in different labs." (PMID 26273832, 2015). "Transmission disequilibrium of CNTNAP2 variants previously associated with ASD and autism related language traits." (PMID 24147096, 2013). "To further evaluate the role of CNTNAP2 in autism, we performed the first gene expression study in post-mortem brain samples of autistic individuals." (PMID 24147096, 2013). "Our studies provide an intriguing initial insight into CNTNAP2 in that the suggested linkage of the gene to autism likely extends beyond simple haploinsufficiency." (PMID 24147096, 2013). "Such overlaps are reflected in evidence for Darwinian positive selection, and recent human-specific changes in otherwise conserved amino acid positions, in genes such as AHI1, CNTNAP2 and FOXP2 that have been associated with risk of autism." (PMID 23639054, 2013). "In corroboration with the general lack of detection of deletions or other CNVs in autism families, all autism brain samples demonstrated CNTNAP2 expression despite the presumptive unstable locus (FRA7I) spanning the gene." (PMID 24147096, 2013). "Using this method we identified associations with SNPs at the P<10−4 level in or near several genes previously implicated in autism: NLGN4X, RAPGEF4, RORA, FAM135B and CNTNAP2." (PMID 24204716, 2013). "Recent studies of disorder reported that variants of the CNTNAP2 gene are associated both with language deficits in specific language impairment (SLI) and with language delays in autism." (PMID 21310003, 2011). "A neurexin gene on chromosome 7, CNTNAP2, has been associated with a range of neurodevelopmental disorders, including SLI and autism." (PMID 21418292, 2011). "We note that the CNTNAP2 gene of recent interest in autism is at 145,444,386 bp, downstream of our peak." (PMID 20678250, 2010). "Cntnap2−/− mice display the core behaviors of autism, hyperactivity, and seizure." (PMID 40826483, 2025). "Thus, behavioral training reduced the early responses to the background in the Shank3B+/− and Cntnap2−/− mice, constituting a mechanism for increasing the neural discriminability of embedded targets within background odors in these two mouse models of autism." (PMID 41062277, 2025). "Moreover, one study reported a significantly lower frequency of miniature inhibitory postsynaptic currents, which reflect IPSPs, across multiple developmental stages in CNTNAP2-knockdown neurons, a model commonly used to study autism pathogenesis." (PMID 41166021, 2025). "Consistent with the pathogenic effect of I1253T mutation in ASD patients, Cntnap2-I1254T knock-in mice displayed characteristic autism-like phenotypes that can be rescued by restoring C79 expression, highlighting the essential function of C79 in CNTNAP2 across species." (PMID 38424048, 2024). "Furthermore, we found that restoring C79 expression improves autism-like phenotypes in the CNTNAP2-I1254T mutant mice and CNTNAP2−/− knockout mice." (PMID 38424048, 2024). "Regarding genetic biomarkers diagnosis, autism-related genes such as SHANK3, NRXN1, and CNTNAP2 exhibit significant complexity and variability, with mutations appearing as single nucleotide polymorphisms (SNPs), small insertions or deletions (Indels), and copy number variations (CNVs)." (PMID 39734494, 2024). "The effect of CNTNAP2 variation on autism may be best understood at the circuit level, as supported also by its association with epilepsy and seizure activity in both humans and rodent models." (PMID 39677787, 2024). "Finally, exogenous expression of C79 improves autism-like phenotypes in the Cntnap2-I1254T knock-in and Cntnap2−/− knockout mice." (PMID 38424048, 2024).
autism (continued). "Although these prior studies have demonstrated the relevance and utility of using human speech sounds in rodent model work, we cannot say with certainty that knockout of Cntnap2 creates the same speech sound perception impairments observed in humans with autism." (PMID 39677787, 2024). "Cntnap2 KO mice represent a well-established genetic model system for autism." (PMID 37582968, 2023). "Our study implicates three ASD-susceptible genes, CNTNAP2, Necdin and CASK, may participate in the autism-related behaviors through a common pathway." (PMID 37271769, 2023). "Utilizing digestion of PNNs in the PFC may restore juvenile-like plastic states in adult mice to reveal improvements in social behavior of CNTNAP2 knockout mouse model of autism." (PMID 36998537, 2023). "Furthermore, BTBR mice are a model of idiopathic autism whereas Cntnap2−/− mice are a model of syndromic autism." (PMID 37596047, 2023). "Research on adult rats lacking the CNTNAP2 gene, associated with language-related disorders such as autism, demonstrated hyperexcitability in the auditory cortex." (PMID 39483200, 2023). "Moreover, several recent studies have shown that genetic ablation of Tau and Tau reduction can attenuate autism-like phenotypes in Cntnap2−/− mice and Dravet syndrome model mice (Scn1aRX/+)." (PMID 37936174, 2023). "Although studies have suggested association or predisposition to ASD in individuals with CNTNAP2 mutations, the role of CNTNAP2 in the pathophysiology of autism is still not clear." (PMID 35628852, 2022). "Therefore, the Cntnap2 rat model for autism does not only have a high construct but also face validity." (PMID 34489651, 2021). "Together, these results indicate that the Cntnap2 mouse model could provide novel insight into the pathophysiological mechanisms of autism core sensory deficits." (PMID 34593517, 2021). "To investigate the effect of gene-environment interaction, we injected VPA into pregnant Cntnap2 heterozygous female mice that had been mated with Cntnap2 heterozygous male mice on embryonic day 10.5 (E10.5) and investigated the autism-like behavioral phenotypes in the resulting offspring." (PMID 31391512, 2019). "Disrupting CNTNAP2 rare variant burden was not higher in autism or schizophrenia compared to controls." (PMID 30586385, 2018). "Moreover, we show that FOXP1 SUMOylation is required for regulation of CNTNAP2 expression, a candidate autism gene involved in dendritic maturation." (PMID 28408745, 2017). "The study reports 3 new findings concerning the Cntnap2 KO mice, an important model of autism." (PMID 28966979, 2017). "Post hoc analyses showed a statistically significant decrease, such that there was a >40% reduction in the mean densities of immature DCX+ neurons in the ventral dentate gyrus in both mouse models of autism compared to wild-type mice (WT vs Cntnap2−/−, p = 0.02; WT vs Shank3+/ΔC, p = 0.02)." (PMID 27785461, 2016). "For example, our ref+ pipeline was able to detect an ALU insertion in the intronic region of CNTNAP2, a gene associated with autism and schizophrenia (the GRC pipeline did not detect this insertion)." (PMID 26322511, 2015). "Using five autism-related mouse models, Shank3+/ΔC, Mecp2R308/Y, Cntnap2−/−, L7-Tsc1 (L7/Pcp2Cre::Tsc1flox/+), and patDp(15q11-13)/+, we report specific perturbations in delay eyeblink conditioning, a form of associative sensory learning requiring cerebellar plasticity." (PMID 26158416, 2015). "However, CNTNAP2 demonstrated both significantly low- and high-expression in autism cases compared to controls (p = 1.9 x10-5)." (PMID 24147096, 2013). "Multiple lines of genetic evidence suggest a role for CNTNAP2 in autism." (PMID 24147096, 2013). "Subsequently, several independent studies using whole genome linkage, association and CNV analysis have demonstrated the role of rare, common and deletion variants at CNTNAP2 as a susceptibility factor for idiopathic ASD and autism, and related language quantitative traits." (PMID 24147096, 2013).